CD4 (CD4 molecule)
Diseases named in the same sentence as CD4 in open-access papers (continued):
Sharing a sentence is not in itself a finding about the gene and the disease.
COVID-19 (continued). "Reduction in total CD45+, CD4+, and CD8+ T-cell frequencies was observed in both COVID-19+ and UN samples over the culture period; TNF-α+-producing CD45+ cells also decreased, but the change was not significant." (PMID 40698364, 2025). "The CD4 + CD45RA+/CD4 + CD45RO+ ratio and the CD8 + CD45RA+/CD8 + CD45RO+ ratio were also negatively correlated with the age of patients with COVID-19." (PMID 40988875, 2025). "It is evident that CD8+ T cells in patients who recovered from COVID-19 and their household members (who were exposed to SARS-CoV-2) became more activated and exhausted than CD4+ T cells after reexposure ex vivo." (PMID 40378227, 2025). "All COVID-19 groups (A, B, C, and D) showed a significantly higher expression of TIM-3 on both CD4+ and CD8+ T cells than the controls." (PMID 40005306, 2025). "In a post-hoc analysis, comparisons of COVID-19 incidence among PLWH between hybrid and vaccine immunity groups were made within strata defined by CD4 count (≥ or <350 cells/μl) and viraemia (HIV viral load ≥ or <50 copies/mL)." (PMID 39902315, 2025). "Both CD3+CD4+ and CD3+CD8+ T cells showed an increasing trend in UN samples when compared to COVID-19+ with M- and S-peptide exposure." (PMID 40698364, 2025). "CD4+ cMet+ T cells from patients with Vacc-AMP and COVID-19 displayed a significant proliferative response to the Kv2.1 peptide." (PMID 41164857, 2025). "The stability of CD4 and CD8 T-cell responses is one of the findings related to recovery from acute COVID-19, with fewer tissue cells presenting T-cell receptors." (PMID 41463036, 2025). "Activation of CD8+ and CD4+ T-cells, as well as the generation of TNF-α, IFN-γ, and IL-2, appears to be a significant effect of COVID-19 vaccinations." (PMID 39931582, 2025). "In this study, we evaluated the induction of SARS-CoV-2–specific CD4+ and, more pertinently, CD8+ T cells as a function of age and disease severity in unvaccinated patients with acute COVID-19 recruited across separate cohorts from France and Japan." (PMID 39847442, 2025). "SARS-CoV-2 infection induces vigorous CD4+ and CD8+ T cell responses against different viral antigens and protection against severe COVID-19 appears to correlate best with the cellular immune compartment." (PMID 39861005, 2025). "In this study, we observed robust circulating CD4+- and CD8+-activated T cells across all ethnic groups 2 years after a third COVID-19 vaccination dose." (PMID 40573938, 2025). "The G>C transition in LINC01276 is expected to disrupt the CD4+ and CD8+ T cell-specific functions in COVID-19 pathophysiology." (PMID 40724930, 2025). "The ability of SARS-CoV-2 S1-stimulated CD4+, CD8+ T, and NK cells from the COVID-19-recovered groups and healthy individuals to express IFN-γ/CD107a as a marker of cytotoxicity was assessed in flowcytometry." (PMID 39963186, 2025). "Seven non-Spike highly conserved antigens were selectively recognized by cross-reactive CD4+ and CD8+ T cells from unvaccinated asymptomatic COVID-19 patients." (PMID 40894020, 2025). "In summary, we have shown that advanced age and systemic inflammation can suppress SARS-CoV-2–specific CD4+ and, to a greater extent, CD8+ T cell immunity in patients with acute COVID-19." (PMID 39847442, 2025). "Our second key finding was that disease-associated inflammation, a distinctive feature of primary infection, inhibited the induction of SARS-CoV-2–specific CD4+ and CD8+ T cells in patients with acute COVID-19." (PMID 39847442, 2025). "We identified an important cell subset of PBMCs, the CD4+ TEM cell cluster, that is specific and exhibits similar functions in PBMCs from both PTB and COVID-19 patients." (PMID 39337460, 2024). "We found a significant decrease in the number of CD3+CD4+ and CD3+CD8+ lymphocytes and the percentage of NK cells in patients with severe COVID-19 on day 1 of admission." (PMID 39595989, 2024).
COVID-19 (continued). "We observed an increase in the CD4+ Effective Memory T Cell (CD4+ TEM) cluster in both PTB and COVID-19 patients according to the single-cell transcriptional landscape of PBMC." (PMID 39337460, 2024). "The expression of CD4 and CD8 was similar, with the exception that convalescent COVID-19 plasma significantly decreased the MFI of CD4." (PMID 38424104, 2024). "For example, a positive correlation has been described between COVID-19 improvement and the dynamic increase of white blood count (WBC), total lymphocytes, total T, CD4+ and CD8+ T cells." (PMID 39595989, 2024). "Pearson correlation analysis was performed to determine the linear correlation between the magnitude of CD4+ T-cell responses directed toward each of the 16 highly conserved SARS-CoV-2 epitopes and the severity of COVID-19 symptoms." (PMID 38605956, 2024). "Other studies support an overall increase in early Effector and Effector Memory for CD4+ and CD8+ T-cell subsets in COVID-19 patients." (PMID 39597661, 2024). "Patients with long COVID-19, in particular, demonstrate increased exhausted CD4+ T cells, persistent cytotoxicity in CD8+ T cells, and persistent T cell activation, though long COVID-19 correlation with T cells is conflicting." (PMID 39178184, 2024). "Studies showed that the changes in peripheral blood CD4+ and CD8+ T cells decreased significantly in severe and critical patients with COVID-19." (PMID 38811907, 2024). "On the one hand, in patients with mild COVID-19, the absolute counts of CD3+CD4+CD25+CD127low Tregs were elevated if compared to healthy control, whereas in patients with severe COVID-19 only relative numbers of Tregs were increased." (PMID 39519310, 2024). "Both expansion and contraction of CD4 and CD8 T cell clones in critically ill patients compared to mild COVID-19 cases have been reported." (PMID 39530088, 2024). "Activated T cells, including the CD4+ T, CD8+ T, and Th cells, were found enriched in COVID-19 participants." (PMID 39077735, 2024). "CD4+ and CD8+ T lymphocytes were significantly decreased in patients with COVID-19, and this had an impact both on the severity of the disease and on the prognosis." (PMID 39100065, 2024). "Naïve CD4 and CD8 cells were also reduced in acute COVID-19, with the partial abrogation of the drop in naïve CD8 cells in the presence of immunosuppression." (PMID 38791279, 2024). "CD4+ T cells from asymptomatic patients or patients with mild disease produce higher amounts of IFN-γ and IL-2 than those from patients with severe COVID-19, indicating a higher functionality and proliferative capacity." (PMID 39460293, 2024). "CD4+ T cells immune responses play an important role in suppressing initial SARS-CoV-2 infections and their correlation with reduced COVID-19 severity." (PMID 39204050, 2024). "Overall, these findings provide evidence for protective roles for circulating SARS2-specific CD4+ and CD8+ T cells during acute COVID-19." (PMID 39704169, 2024). "The immune cell imbalance is also evident in the impairment of CD4+ T cell function and the overactivation of CD8+ T cells in COVID-19, leading to a depletion of cell counts." (PMID 38464514, 2024). "Despite the limited number of participants, SARS-CoV-2-specific CD4+GRB+ values were found to be distinct among MIS-C, COVID-19, and healthy controls and were specifically lower in acute MIS-C compared to COVID-19 but higher compared to healthy controls." (PMID 39594853, 2024). "On the other hand, CD4 and CD8 cells expressing CD38 were also observed in COVID-19 patients and related to severity, suggesting that the role of these cells in antiviral response is critical." (PMID 39519178, 2024). "By contrast, CD39+CD3+CD45+ (p = 0.0004), CD39+CD4+CD3+CD45+ (p = 0.016), and CD39+CD8+CD3+CD45+ (p = 0.0089) cells were significantly increased in COVID-19 patients." (PMID 38793691, 2024).
COVID-19 (continued). "The exhausted phenotype with decreased counts of CD4 + T cells and CD8 + T cells were seen in severe course of COVID-19, resulting a reduced CTL functionality." (PMID 38678181, 2024). "Moreover, CD4+CD25+ T and CD8+CD25+ T cells (% and MFI) were increased in COVID-19 convalescent patients, while the frequency of CD4+CD62L+ T and CD8+CD62L+ T cells was decreased, suggesting that T cells in COVID-19 convalescent patients may be prone to activation." (PMID 38424104, 2024). "The CD4+IL-17/million CD3+ median (IQR) values were higher in children with MISC_A compared to MISC_C (p-value: 0.03), COVID-19 (p-value: 0.03), and controls (p-value: 0.03)." (PMID 39594853, 2024). "In the first wave, moderate and severe COVID-19 patients showed significantly higher levels of granzyme B (GZMB) and expression of CD107a in CD8 cells and CD39 and PD-1 in conventional CD4+ T cells compared to healthy individuals." (PMID 39519178, 2024). "Characterizing the CCCs/SARS-CoV-2 cross-reactive memory CD4+ and CD8+ T cells in unvaccinated COVID-19 patients is a difficult task today because over 85% of adults are currently vaccinated." (PMID 38605956, 2024). "Twenty-two (73%) studies reported high COVID-19 vaccine seroconversion rates in PWH, although PWH with lower baseline CD4 counts and CD4/CD8 ratios and higher baseline viral loads had lower seroconversion rates and antibody titres." (PMID 38793698, 2024). "Enrichment analyses also demonstrated a connection between markers of CD4+ TEM cells, the T cell receptor, and COVID-19." (PMID 39337460, 2024). "Towards this goal, we investigated the dynamics of spike-specific CD4+ and CD8+ T-cell responses elicited after two and three doses of COVID-19 vaccine in a cohort of 50 adult PLWH receiving antiretroviral therapy and 87 control participants without HIV." (PMID 38793543, 2024). "The results demonstrated that, at D0, nine cell subsets presented robust global accuracy (AUC ≥ 0.8) to classify COVID-19 vs. HCs, with outstanding performance (AUC = 0.9) observed for CD8+CD69+, CD4+CD38+, CD3+CD38+ and CD8+CD27+." (PMID 39597661, 2024). "Unlike for CD8+ T cells, higher frequencies of multifunctional CCCs/SARS-CoV-2-cross-reactive memory CD4+ T cells, expressing CD69, CD107a/b, and TNF-α were detected in COVID-19 patients compared to healthy individuals." (PMID 38605956, 2024). "In ARDS patients, the proportion of both CD4+ and CD8+ Tregs is increased and variation in the amount of Treg cells is observed in mild COVID-19 patients compared to those which were hospitalized." (PMID 38863829, 2024). "The mean fluorescence intensity (MFI) of CD25 in CD4+ T and CD8+ T cells upon stimulation with either S or N protein was significantly increased in convalescent COVID-19 patients." (PMID 38424104, 2024). "The levels of COVID-19 microenvironment markers, i.e., CD3, CD4, CD8, CD20, CD68, vimentin, NP, ACE2, Granzyme B, E-cadherin, and phosphorylated nuclear factor kappa B (p-NFκB), were measured via IMC." (PMID 39100091, 2024). "A significant reduction of peripheral CD4+ and CD8+ T cells and NK cells has been described in patients with severe and critical COVID-19." (PMID 39595989, 2024). "On multivariable analysis, however, only high expression of CD39+CD45+ (OR 51.4, 95% CI 1.5 to 1763) and TIM3+CD39+CD4+CD3+CD45+ (OR 22.6, 95% CI 1.8 to 277) cells was an independent predictor for severe COVID-19 including the cases with fatal outcomes." (PMID 38793691, 2024). "We then explored and compared the phenotypic identity of CD4+ and CD8+ T-cell subsets present in the blood of COVID-19 patients at baseline and on day 7 in a bid to determine how TPE impacted the ongoing T-cell response." (PMID 39896810, 2024). "Accumulating evidence has confirmed that COVID-19 vaccination can elicit a satisfactory immune response in PWH comparable to that of the general population, except for cases with low CD4 count recovery." (PMID 39772028, 2024).
COVID-19 (continued). "The flow cytometric evaluation of TIM3+CD39+CD4+CD3+CD45+, as well as CD39+CD45+, is a powerful tool for the prognostication of COVID-19 patients on hospital admission." (PMID 38793691, 2024). "SARS-CoV-2-specific CD4+ and CD8+ T cells play an important role in viral clearance and recovery from COVID-19 (23, –25)." (PMID 39284068, 2024). "Peripheral immune cells (CD3+ T, CD4+ T, CD8+ T, natural killer, and CD19+ T) were detected following allo-HSCT in 76 patients with COVID-19 (56 with mild disease and 20 with moderate-to-severe disease)." (PMID 38481430, 2024). "PLWH saw a brief decline in CD4+, and CD8+ counts during the acute phase of COVID-19 with the CD4+/CD8+ ratio remaining unchanged." (PMID 38628843, 2024). "Our previous studies have shown that COVID-19 booster shots are effective in PWH, resulting in increases in CD4 cell counts and neutralizing antibodies that last for up to six months." (PMID 39772028, 2024). "Studies also show that CD44 is highly expressed in CD4+ and CD8+ T cells of severe COVID-19 patients, which further supports the interconnected relationships these proteins have within the immunological response to COVID-19." (PMID 39334929, 2024). "PWH hospitalized for acute COVID-19 had decreased expression of TIM3 and trended toward decreased expression of OX40 on CD4+ T cells (P ≤ 0.05 and P = 0.057, respectively)." (PMID 38408318, 2024). "Overall, we confirmed an upregulation of the MIF receptor CD74 in CD4+ and CD8+ T cells in critically ill COVID-19 patients." (PMID 38992165, 2024). "Regarding cell-mediated immunity, studies have shown that both helper CD4+ T cells and cytotoxic CD8+ T cells perform crucial roles in vaccine-induced protection against COVID-19." (PMID 38793745, 2024). "The present study has comprehensively characterized CCCs/SARS-CoV-2 cross-reactive memory CD4+ and CD8+ T cells in blood samples from over 140 unvaccinated symptomatic and asymptomatic COVID-19 patients." (PMID 38605956, 2024). "Reduced lymphocytes, particularly CD4+CD8+ T lymphocytes, have been found in patients with early-stage COVID-19." (PMID 38202265, 2024). "In COVID-19 group, NK cells (CD56+) and helper CD4+ T cells (Th1 and Th2) were found in the lungs of deceased patients and, with increased frequency in peripheral blood, were related to the inflammatory phase." (PMID 39483459, 2024). "Immunohistochemical examination of the vermiform appendages in children with confirmed COVID-19 revealed a predominance of CD3+, CD4+, CD20+, CD138+, CD 163+, and CD68+ cells compared to acute appendicitis without COVID-19 infection and the control group." (PMID 38397914, 2024). "In addition, there were 266 DEGs in CD14 Mono, and we further clustered CD4 Mono into four subpopulations and tried to identify MS1 related subpopulations, which have been reported to be associated with severe COVID-19 and sepsis, and their changes at six months after infection are unknown." (PMID 38503738, 2024). "In contrast, low frequencies of unvaccinated severely ill COVID-19 patients and unvaccinated patients with fatal outcomes significant IFN-γ+CD4+, and IFN-γ+CD8+ T-cell responses specific to α-CCCs/SARS-CoV-2 cross-reactive epitopes (p < 0.001)." (PMID 38605956, 2024). "Comparisons of blood from healthy subjects (unexposed) and patients with COVID-19 revealed that the percentage of circulating NK (CD56+) and CD4+ T cells significantly increased at 20–30 days after the onset of symptoms." (PMID 39483459, 2024). "Recent CD4 counts and CD4/CD8 ratios were lower than after COVID-19 but remained higher than before COVID-19 in vaccinated PWH." (PMID 39772028, 2024). "All other measured parameters, including CD3+CD4+ T cell count, CD3+CD8+ T cell count, CD3-CD19+ B cell count, and CD3+CD56+ NK cell count, were significantly lower in COVID-19 patients compared to the control group." (PMID 38464514, 2024).
COVID-19 (continued). "The proliferation of CD4 TCM cells in both healthy subjects and COVID-19 patients highlights their protective role in developing viral infection." (PMID 39530088, 2024). "In particular, the M, S, and N proteins are codominant in natural infection, each being recognized by CD4+ and CD8+ T cells in the vast majority of human COVID-19 survivors." (PMID 38675761, 2024). "In case of the T cells (including CD4+ T and CD8+ T cells) recognize, in addition to the nucleocapsid and spike protein, membrane proteins (M) of the virus and are present in most COVID-19 patients." (PMID 38572317, 2024). "Collectively, these results show that, 7 days after the start of treatment, strong activation/proliferation of CD4+Tem, CD8+Tem and CD8+Temra cell subsets were still evident in COVID-19 patients." (PMID 39896810, 2024). "To gain a deeper understanding of CD68+ macrophages and their interactions with CD4+ and CD8+ cells, we conducted RNA-seq analysis of COVID-19 GI tissues and WGCNA to identify key hub genes." (PMID 39100091, 2024). "It has been shown that B-NHL patients on anti-CD20 antibody monotherapy or anti-CD19 CAR T treatment are able to mount potent S-specific CD4+ and CD8+ T lymphocyte responses following COVID-19 mRNA vaccination, despite impaired humoral responses." (PMID 39339993, 2024). "Lastly, in a cohort of 30 COVID-19 patients, CD74 surface expression was found to be significantly upregulated on CD4+ and CD8+ T cells in patients with severe compared to patients with only mild disease course." (PMID 38992165, 2024). "This encouraging finding suggests COVID-19 vaccination provides substantial protection against severe disease in PLWH, even among those with lower CD4 counts." (PMID 39772116, 2024). "IL-17 expressed by either CD4+ or CD8+ T cells possibly plays a key role in MIS-C pathogenesis, as children with acute MIS-C had higher IL-17 values compared to convalescent COVID-19 or MIS-C patients." (PMID 39594853, 2024). "Meanwhile, the correlation analysis of ICD-related DEGs and immune cell infiltration in severe COVID-19 showed that TLR4, PIK3CA, FOXP3, ENTPD1, CD4, CASP1 and BAX were significantly correlated with a variety of immune cell infiltration." (PMID 38600309, 2024). "COVID-19 can increase the expression of TRAIL and its receptors in uninfected CD4+ and CD8+ lymphocytes, followed by a substantial reduction in lymphocyte count." (PMID 39290698, 2024). "Conversely, examining the impact of HIV on COVID-19 clinical outcomes in PWH on effective ART (i.e., virally suppressed with restored CD4 counts) has yielded variable findings." (PMID 37821620, 2024). "The most commonly used sets of markers for CD4 + T cells were OX40 and CD137, and CD69 and CD137 for CD8 + T cells in case of COVID-19 studies." (PMID 38167915, 2024). "COVID-19 has disrupted regular HIV care and follow-up significantly, impacting key aspects such as in-person consultations, viral load testing and CD4 counts." (PMID 39486827, 2024). "In contrast, higher frequencies of functional CD4+ and CD8+ T cells specific to CCCs/SARS-CoV-2 epitopes were detected in unvaccinated asymptomatic COVID-19 patients." (PMID 38605956, 2024). "In contrast, we found a transient increase in CD4 count and CD4/CD8 ratio after COVID-19 vaccination." (PMID 39772028, 2024). "Compared with non-severe patients, a statistically significant reduction in CD4+ T cells, CD8+ T cells, NK cells, and monocytes was observed in patients with severe COVID-19 (p<0.05)." (PMID 39679195, 2024). "PD1, TIM3, and LAG3 expression was significantly increased in all cell subsets of COVID-19 patients when compared with healthy controls, except for TIM3+CD4+CD3+CD45+ (p = 0.64), TIM3+CD8+CD3+CD45+ (p = 0.41), and TIM3+CD39+CD8+CD3+CD45+ (p = 0.060)." (PMID 38793691, 2024).